BRAF (B-Raf proto-oncogene, serine/threonine kinase)
Diseases named in the same sentence as BRAF in open-access papers (continued):
Sharing a sentence is not in itself a finding about the gene and the disease.
thyroid cancer (continued). "Since the approval of sorafenib, the new and more specific BRAF inhibitor dabrafenib has been assessed in clinical trials in radio-iodine refractory thyroid cancer, with lower incidence of adverse events and greater therapeutic outcomes." (PMID 37803074, 2023). "Co-delivery of Da and Dox by SPNs exhibited the strongest therapeutic effect in vitro and in vivo by inhibiting ERK phosphorylation in BRAF V600E mutant thyroid cancer cells." (PMID 37153748, 2023). "Third, to our knowledge, this is one of the first studies on native Bangladeshi patients with thyroid cancer to comprehensively study a difference of methylation between BRAF wild-type and BRAF mutant thyroid cancer patients." (PMID 36975440, 2023). "Our data, taken together, demonstrate that STAG2 inactivation reprograms glutamine metabolism of BRAF-mutant thyroid cancer cells, thereby improving their cellular response to glutaminase inhibitor." (PMID 37479689, 2023). "Regarding targeting BRAF mutant thyroid cancer cells, it was shown that vitamin C plays its antitumour effect through inhibition of MAPK/ERK and PI3K/AKT pathway which was mediated by ROS‐dependent manner." (PMID 37246589, 2023). "-The clinical utility of BRAF, KRAS, NRAS, and TERT promoter mutation analysis on ctDNA appeared to be limited to early-stage thyroid cancers." (PMID 37762070, 2023). "The BRAF status of thyroid cancer patients is of great importance, both in terms of prognosis and treatment plan." (PMID 38076095, 2023). "Mechanistic studies have also revealed that vitamin C inhibits the MAPK/ERK and PI3K/AKT signalling pathways in BRAF wild‐type or mutant thyroid cancer cells." (PMID 37246589, 2023). "In this context, methylation data from our current study indirectly suggests an opportunity for potential use of PDL1 inhibitor in BRAF mutant thyroid cancer." (PMID 36975440, 2023). "Surprisingly, we find that STAG2 knockdown makes BRAF-mutant thyroid cancer cells more sensitive to glutamine deprivation or glutaminase inhibitor via the ERK/AKT/GSK3β/c-Myc feedback axis." (PMID 37479689, 2023). "BRAF is the most commonly mutated gene, and KRAS mutations are the second most common genetic alterations in well-differentiated thyroid cancers." (PMID 37185420, 2023). "For instance, only two known cancer genes were found to be mutated in over 5% of thymomas (MUC16 and HRAS), testicular germ cell tumours (KRAS and KIT), and thyroid carcinomas (BRAF and NRAS)." (PMID 37550388, 2023). "The aim of this study was to assess the feasibility of targeted radionuclide therapy of thyroid carcinoma, first exploring potential targets BRAF, EGFR and CD44v6 in patient material through immunohistochemistry (IHC) and pyrosequencing." (PMID 38076095, 2023). "The aim of this study was to assess the feasibility of targeted therapy of thyroid carcinoma, first exploring potential targets BRAF, EGFR and CD44v6 in patient material through immunohistochemistry and mutation analysis." (PMID 38076095, 2023). "B-raf inhibitors (BRAFi) are effective for BRAF-mutated papillary (PTC) and anaplastic (ATC) thyroid carcinomas, although acquired resistance impairs tumour cells’ sensitivity and/or limits drug efficacy." (PMID 37198319, 2023). "BRAF alterations other than the p.V600E are less common in thyroid carcinoma and represent an alternative mechanism of BRAF activation with unclear clinical significance." (PMID 36835466, 2023). "BRAF is known to play important regulatory roles in the proliferation and differentiation of thyroid cancer." (PMID 35865459, 2022).
thyroid cancer (continued). "Increased fibroblast infiltration around the tumor area has been found not only in human thyroid cancer tissues but also in mouse thyroid cancer models, both induced by oncogenic BRAF." (PMID 36293435, 2022). "Treatment of BRAF-mutant thyroid cancer cells with RAF kinase inhibitors resulted in YAP nuclear translocation and activation of its transcriptional output." (PMID 36476495, 2022). "In conclusion, BRAF-mutant thyroid cancer cells with constitutive activation of YAP transcriptional activity have intrinsic resistance to RAF kinase inhibitors, driven in part by increased expression of the upstream components of the NRG1 signaling pathway." (PMID 36476495, 2022). "Another phase II clinical trial of nivolumab (a PD-1 inhibitor) is being conducted in metastatic radioiodine-resistant BRAF V600E-positive thyroid cancer (clinicaltrial.gov.in NCT04061980)." (PMID 36518249, 2022). "From the clinical perspective, dabrafenib, a specific BRAF kinase inhibitor, displayed only transient clinical benefit for BRAF-mutant thyroid cancer and finally became ineffective." (PMID 35515000, 2022). "Lapatinib, a pan HER2/HER3/EGFR inhibitor, cooperated with vemurafenib to inhibit growth of BRAF-mutant thyroid cancer cell lines, an effect that was enhanced by YAP silencing." (PMID 36476495, 2022). "In summary, we identified differentially expressed genes and signaling pathways in thyroid cancer patients carrying mutant BRAF." (PMID 35123502, 2022). "This was likely due to the low prevalence of the BRAF mutation in the malignancies related to the indeterminate cytology, where RAS-like thyroid cancers are the most common." (PMID 36358788, 2022). "BRAF inhibitors combined with immune checkpoint inhibitors (ICIs) were reported to significantly inhibit thyroid cancer growth and prolong survival in mouse models." (PMID 36675746, 2022). "A future research direction could be to investigate the interaction of the BRAF V600E mutation with other somatic genetic alterations in various signaling pathways, which could provide novel diagnostic and prognostic molecular markers and therapeutic targets for thyroid cancer." (PMID 35755312, 2022). "The expanded gene mutation panel of the DNA‐RNA test contributed greatly to the diagnosis of thyroid cancer based on the specific molecular alteration detected (e.g. BRAF V600E), which is important for a ‘rule‐in’ test." (PMID 35247035, 2022). "For instance, in 8505C cells vemurafenib treatment increases pHER2 and pHER3 levels, whereas pEGFR levels decline, consistent with previous evidence that HER3/HER2 heterodimers are the primary mediators of ERK rebound in BRAF-mutant thyroid cancer cells." (PMID 36476495, 2022). "Other studies showed much lower prevalence of BRAF V600E mutations (14.3%) and NRAS mutations (21.4%) in acromegalic patients with thyroid cancer." (PMID 37435457, 2022). "How such divergent tumor growth patterns arise from constitutive activation of the same signaling pathway, driven by BRAF and RAS mutations in human thyroid cancer cells, remains a key question." (PMID 34379110, 2022). "Combined inhibition of BRAF and HER3 using Vemurafenib and the human monoclonal antibody CDX-3379, respectively, would restore radioiodine (RAI) avidity by potently inhibiting MAPK activation in patients with BRAF-mutant iodine refractory thyroid cancer." (PMID 35631627, 2022). "The immune escape mechanism of thyroid cancer is complicated and mainly involved the downregulation or loss of function of MHC-1 and upregulation of PD-L1 and BRAF." (PMID 35935973, 2022). "In this study, a comprehensive bioinformatics analysis was performed to identify the differentially expressed genes and signaling pathways in thyroid cancer patients carrying mutant BRAF." (PMID 35123502, 2022).
thyroid cancer (continued). "We performed mutational analyses for BRAF and the TERT promoter in thyroid cancer patients who had undergone surgery at our institution since 2019." (PMID 36230856, 2022). "There was no significant change in survival time compared with high WT1 expression and low WT1 expression in BRAF wild-type thyroid cancer patients." (PMID 35123502, 2022). "A volcano plot demonstrates the differentially expressed genes (DEGs) in thyroid cancer patients with mutant and wild-type BRAF in the TCGA cohort." (PMID 35123502, 2022). "Intrinsic resistance to vemurafenib in BRAF-mutant thyroid cancer cell lines has been shown to be due to attenuation of the negative feedback by vemurafenib on the NRG1-HER3/HER2 pathway, with the consequent reactivation of ERK." (PMID 36476495, 2022). "RET fusions are mutually exclusive with BRAF and RAS gene mutations in thyroid cancer, consistent with its role as a driver oncogene." (PMID 35510953, 2022). "As a single tertiary center, mutational analyses for BRAF and TERT promoter in all thyroid cancer patients have been implemented in our institution since 2019." (PMID 36230856, 2022). "In various thyroid cancer contexts, there is a strong correlation between the BRAF-RAS score from the thyroid cancer TCGA or ERK output signatures with the cluster 2 YAP signature shown to be most proximal to YAP activation." (PMID 36476495, 2022). "As a paradigm, the prevalence of cfBRAFV600E in BRAF-mutated PTC, the most common cfDNA analysis performed in thyroid cancer, is widely variable between different series." (PMID 36358788, 2022). "The activation of the receptor tyrosine kinase erbB-3 (HER3) mitigates the MAPK activation achieved by BRAF inhibitors in BRAFV600E mutant thyroid cancers." (PMID 35631627, 2022). "Intriguingly, vemurafenib treatment of BRAF-mutant thyroid cancer cell lines induced translocation of Yap to the nucleus and activation of its transcriptional output, which included key effectors in the NRG1 signaling pathway." (PMID 36476495, 2022). "Sankey plot indicated the relationship between TNM stage, BRAF mutated status and WT1 expression in thyroid cancer patients." (PMID 35123502, 2022). "More importantly, in a previous study, the BRAFV600E mutant notably activated the MAPK signaling pathway in BRAF-mutant thyroid cancers." (PMID 35123502, 2022). "DriverML predicted that BRAF and NF1/PMS2 mutations are the main driving mutations in thyroid cancer, and they play a certain role in regulating its development." (PMID 35865459, 2022). "In the past 5–10 years, as the understanding of the molecular mechanisms underlying thyroid cancer has increased, several biomarkers have been developed for the diagnosis of thyroid cancer, including RET/PTC, RAS, and BRAF mutations." (PMID 36313748, 2022). "BRAF inhibitors such as dabrafenib and vemurafenib have been largely investigated in the treatment of advanced thyroid cancer." (PMID 35600349, 2022). "BRAF V600E and PIK3CA E542K were predominantly associated with thyroid cancer and ovarian cancer, respectively, whereas ERBB2 amplification, BRCA1/2 variant, and KRAS G12C were widely detected across various cancer types." (PMID 36088851, 2022). "PTC is often characterized by RET chromosomal rearrangement, or point mutation of RAS or BRAF proto-oncogenes, all of which are able to trigger the activation of MAPK cascade and therefore the appearance of thyroid carcinoma." (PMID 35453992, 2022). "In conclusion, aggressive variants of PTC had a higher prevalence of BRAF mutation (89%) and lower prevalence of RAS mutation (3%) than other thyroid cancers." (PMID 33672707, 2021). "BRAF, RAS, and TERT mutations are highly prevalent in metastatic differentiated thyroid cancer and are concordant between primary and metastatic cancers." (PMID 34319022, 2021).
thyroid cancer (continued). "This is consistent with the notion that in thyroid cancer cell lines, as well as in advanced thyroid cancers, the BRAF-/RAS-like classification is preserved but the two subtypes exhibit less profound differences and reduced BRS values." (PMID 34072194, 2021). "BRAF, as a member of serine/threonine protein kinase family, participates in MAPK/ERK signaling pathway in cells, and its mutation is related to thyroid canceration." (PMID 34697553, 2021). "v-Raf murine sarcoma viral oncogene homolog B1 (BRAF) V600E mutation is the most common genetic mutation in papillary thyroid carcinoma (PTC); it is associated with thyroid cancer by activating the mitogen-activated protein kinase pathway." (PMID 34926235, 2021). "Here, we performed an analysis on the role of FRMD5 in thyroid cancer, as we found significant discrepancies in FRMD5 expression between BRAF- and RET-mutated PTCs, as well other types of TCs (TCGA and microarray data analysis of clinical specimens)." (PMID 34201607, 2021). "Targeting autophagy in this model sensitized the BRAF-mutant thyroid cancer cells to vemurafenib in cell culture and xenografts." (PMID 34298710, 2021). "By using a combination of genetic and pharmacological approaches, we found that pSMAD activation is increased in BRAF-mutant thyroid cancers, and that this is due to promiscuous engagement of activin and TGFβ family ligands with their corresponding receptors." (PMID 33890869, 2021). "The unique oncogene duet of coexisting BRAF V600E and TERT promoter mutations is widely proven to be a robust genetic background promoting thyroid cancer aggressiveness." (PMID 35284335, 2021). "Mutations in BRAF and RAS are thought to represent an early event in the progression of thyroid cancer, given that they are present in poorly and well-differentiated thyroid cancer, as well as in ATCs." (PMID 34359735, 2021). "Treatment with a combination of anti-PD-1/PD-L1 and BRAF inhibitors significantly reduced the tumor volume in a mouse model of thyroid cancer." (PMID 34266418, 2021). "In the setting of advanced and dedifferentiated thyroid cancer, the testing of genetic alterations in genes other than BRAF and RAS (virtually, easily evaluable in all molecular pathology laboratories) is acquiring an increasing importance." (PMID 33799953, 2021). "The clinical utility of BRAF, KRAS, NRAS, and TERT promoter mutation analysis on ctDNA appears to be limited to early-stage thyroid cancers." (PMID 33915745, 2021). "Our previous study has reflected that Vitamin C killed thyroid cancer cells, especially with mutant BRAF, through a ROS dependent inhibition of MAPK/ERK and PI3K/AKT pathways." (PMID 33468157, 2021). "The estimated MSC was the highest for BRAF V600E in thyroid cancer (THCA), followed by BRAF V600E in skin cutaneous melanoma (SKCM)." (PMID 34424899, 2021). "Dabrafenib is a BRAF inhibitor studied in a large phase I clinical trial in patients with metastatic BRAFV600E-mutant thyroid cancer." (PMID 34944814, 2021). "β-Catenin inhibitors can obviously inhibit the resistance of thyroid cancer cells to BRAF (V600E) inhibitors, thus inhibiting the occurrence of EMT." (PMID 34930256, 2021). "Molecular testing has been increasingly utilized to assist with indeterminates as approximately seventy percent of differentiated thyroid cancers have detectable abnormalities involving BRAF, RAS, RET/PTC, or PAX8/PPAR gamma." (PMID 33763983, 2021). "BRAFV600E-mutant thyroid cancers have a high MAPK output because this class 1 BRAF-mutant signals as a monomer and is insensitive to the negative feedback effects of ERK on activated RAF dimers." (PMID 33890869, 2021).
thyroid cancer (continued). "Apart from clinicopathological characteristics, several genic features (such as BRAF, TERT, and RET) can be applied for risk stratification and prognostic scoring systems of thyroid cancer patients." (PMID 35433709, 2021). "It has also been shown that BRAF V600E mutation is significantly associated with the expression of GLUT-1 and glycolysis in thyroid cancer." (PMID 33413689, 2021). "In this study, to better understand the molecular processes involved in BRAF inhibitors drug response, we investigated in vitro the two BRAF inhibitors Vemurafenib and Dabrafenib on BRAFV600E mutated thyroid cancer cell lines." (PMID 34072194, 2021). "GANT61 also inhibited BMI1 and SOX2 expression in WRO82 cells, a third thyroid cancer cell line with wild-type BRAF gene." (PMID 33499351, 2021). "Although administration of BRAF inhibitors such as vemurafenib has shown promising results for RAI-refractory thyroid cancers, the occurrence of adverse effects and primary and/or acquired resistance often limit its applicability for targeted therapy." (PMID 33995657, 2021). "BRAF V600E/K mutant thyroid cancer was also predicted to be more sensitive to Dabrafenib (p < 0.0001)." (PMID 34548481, 2021). "There have been varying reports of the detection of BRAF (V600E) ctDNA in plasma of patients with thyroid cancer." (PMID 34475951, 2021). "It is also possible that this group would benefit more from novel redifferentiation drugs ahead of radioiodine therapy, such as MEK and BRAF inhibitors, which have shown an ability to restore and increase iodine avidity in thyroid cancer." (PMID 34298840, 2021). "Specific molecular targets currently available for the treatment of thyroid cancer include BRAF, RET, MEK, and NRTK." (PMID 35008368, 2021). "In this regard it is remarkable that these differences are more pronounced in individual cancer types with high frequencies of BRAF V600E (e.g. thyroid cancer, THCA) or IDH R132H (e.g. low-grade glioma, LGG)." (PMID 33556087, 2021). "In conclusion, aggressive variants of PTC had higher BRAF and lower NRAS mutation prevalence than other thyroid cancers." (PMID 33672707, 2021). "Mice with a transgenic thyroid expression of RET fusion genes develop papillary-type thyroid carcinoma with no apparent sex bias and transgenic thyroid expression of mutant BRAF leads to the development of thyroid cancer, with dedifferentiation in some cases." (PMID 34884794, 2021). "MAPK and PI3K/AKT pathways are dependent on activity of mutually exclusive RAS, BRAF and RET/PTC point mutations (BRAF/RAS/PIK3CA) and rearrangements (RET/PTC and TRK) which drive thyroid cancer oncogenesis." (PMID 34062862, 2021). "Limited data are available on the diagnostic utility of circulating tumor DNA (ctDNA) in early-stage thyroid cancers for BRAF, KRAS, NRAS, and TERT promoter mutations, which are known detectable markers for thyroid cancers." (PMID 33915745, 2021). "We found that SMAD phosphorylation was induced in mouse BRAFV600E-PTCs, and that a TGFβ transcriptional output signature was present in advanced RAI-refractory human BRAF-mutant thyroid cancers." (PMID 33890869, 2021). "In this study, targeted inhibition of oncogenic BRAF with vemurafenib potently radiosensitized BRAF mutant thyroid cancer cells in vitro and in vivo." (PMID 34537078, 2021). "In this study, we assess by a high throughput analysis the global gene expression profiles of thyroid cancer cells treated in parallel with two BRAF inhibitors." (PMID 34072194, 2021). "In summary, our study shows that BRAF (V600E) ctDNA can potentially be used as a marker of aggressive disease and as a surveillance marker in a subset of thyroid cancers." (PMID 34475951, 2021).